CTCF (CCCTC-binding factor)
Diseases named in the same sentence as CTCF in open-access papers (continued):
Sharing a sentence is not in itself a finding about the gene and the disease.
glioma (26 papers, 2011 to 2025). A benign or malignant brain and spinal cord tumor that arises from glial cells (astrocytes, oligodendrocytes, ependymal cells). "Besides being associated with global promoter hypermethylation, IDH1 mutation facilitated changes in 3D DNA-conformation by CTCF-anchor methylation and upregulated oncogene expression in glioma, correlating with poor prognosis." (PMID 36411356, 2023). "In IDH mutant gliomas, this loss is a consequence of CTCF anchor site methylation." (PMID 32619008, 2020). "Indeed, we found that the inability of CTCF to bind to its recognition motif at the human Rb promoter causes accelerated DNA methylation and epigenetic silencing in transgenes and in glioma cells." (PMID 21663659, 2011). "In gliomas, IDH1 mutations disrupt chromosomal neighborhoods through CTCF hypermethylation, while YY1 mediates chromatin loops and transcription elongation." (PMID 40565099, 2025). "Hypermethylation of CTCF insulators has been shown to cause overexpression of PDGFRA, an oncogene that contributes to tumor proliferation and invasion in glioma." (PMID 39491527, 2024). "Flavahan and colleagues have demonstrated that glioma CpG island methylator phenotype (G-CIMP) is linked to hypermethylation at sites for cohesion and CCCTC-binding factor (CTCF), leading to the reduced affinity of this protein." (PMID 37296846, 2023). "ChIP-seq analysis of glioma samples showed that CTCF has several strong binding sites surrounding OBI1-AS1." (PMID 35260196, 2022). "This is consistent with our human glioma scATAC-seq data, in which CTCF recognition motifs are the most over-represented in ATRX-wildtype specimens." (PMID 34763709, 2021). "To test if ATRX mediates CTCF binding in IDH-mutant glioma we performed anti-CTCF single-cell Cleavage Under Targets and Tagmentation (scCut&Tag) on ATRX wildtype (scrambled control) and KO SB28+IDH1R132H cells." (PMID 34763709, 2021). "CTCF binding sites seem to be a target of altered epigenetic enzymes, as seen in the case of IDH mutant gliomas, which exhibit hypermethylation at CTCF-cohesin binding sites." (PMID 32503656, 2020). "We initially focused on CTCF-bound insulators that demarcate a TAD boundary upstream of a known glioma oncogene, PDGFRA." (PMID 31534142, 2019). "To further assess the contribution of CTCF to the protection of the Rb promoter against DNA methylation, we analyzed a series of glioma cell lines." (PMID 21663659, 2011). "Notably, in gliomas with IDH gain-of-function mutations, hypermethylation of CTCF sites at insulator elements prevents binding to also disrupt boundary formation." (PMID 38724522, 2024). "Likewise, in the scATAC-seq of murine IDH-mutant gliomas, we also observed significant enrichment for CTCF and CTCFL motifs in the peaks that were specific to ATRX-wildtype tumors, but we found no enrichment in ATRX-KO peaks." (PMID 34763709, 2021). "One such mechanism in glioma may be through methylation-induced disruption of a CCCTC-binding factor (CTCF) binding site, resulting in aberrant activation of platelet-derived growth factor receptor alpha (PDGRFA)." (PMID 29616301, 2018). "This hypothesis has been recently corroborated by the finding that DNA hypermethylation causes reduced CCCTC-binding factor (CTCF) binding to DNA, leading to aberrant activation of the oncogene Platelet-derived growth factor receptor (PDGFRA) in gliomas." (PMID 27117029, 2016). "Among these TFs, CTCF, POLR2A, SIN3A, and SPI1 concurrently regulated all five prognostic genes in glioma." (PMID 39491527, 2024). "In Isocitrate Dehydrogenase-mutant (IDH-mutant) gliomas, extensive DNA hypermethylation reduces the binding capacity of the transcriptional repressor, CCCTC-binding Factor (CTCF), leading to impaired insulator function." (PMID 39605897, 2024). "The full impact of CTCF and other TAD organizers on the dysregulated gene expression in gliomas remains to be investigated." (PMID 30644073, 2019).
Intellectual disability (22 papers, 2014 to 2025). "Emerging CTCF-related neurodevelopmental disorders resulting from numerous de novo heterozygous CTCF mutations frequently manifest as syndromic intellectual disability and neurodevelopmental delay such as microcephaly." (PMID 39988079, 2025). "The important role of CTCF/cohesin in regulating cPcdh gene expression suggests a neuropathogenic explanation for syndromic intellectual disability from CTCF/cohesin mutations." (PMID 39988079, 2025). "The initial genetic study of CTCF mutations reported that four patients had different de novo mutations at the CTCF locus and exhibited intellectual disability, microcephaly, or growth retardation; in addition, two patients showed autistic behaviour." (PMID 36447271, 2022). "Given that mutations in cohesin and CTCF cause intellectual disability in humans, the extent to which deficits in cohesin function alter neuronal gene expression remains a critical underexplored question." (PMID 35471149, 2022). "Individuals with de novo mutations in CTCF gene, which leads to haploinsufficiency for CTCF, have an intellectual disabilities, autistic features, microcephaly, and growth retardation." (PMID 35379308, 2022). "Variants in the CTCF gene have been associated with intellectual disability of varying severity, feeding difficulties and below normal head circumference and/or body height (SCV000491326.2; SCV001140119.1)." (PMID 36085161, 2022). "In humans with heterozygous CTCF mutations exhibiting an intellectual disability, specific CTCF sites exhibited DNA hypermethylation." (PMID 30513694, 2018). "Children born with mutations or deletions in CTCF display intellectual disability, microcephaly and often show autistic features, and CTCF was also identified recently as a schizophrenia susceptibility gene." (PMID 29541020, 2018). "CTCF is a highly-conserved transcription factor, and rare loss-of-function variants or deletions of the gene are associated with low birth weight, postnatal growth retardation, microcephaly and intellectual disability." (PMID 33413077, 2021). "CTCF mutations in humans are linked to microcephaly and intellectual disability." (PMID 33692996, 2021). "Moreover, C-JUN is involved in brain development, while CTCF is associated with autistic behavior and intellectual disability." (PMID 30930929, 2019). "Germline CTCF mutations are responsible for a specific phenotype in humans; this phenotype is syndromic intellectual disability with microcephaly and growth retardation; the reported mutations are frameshift and missense mutations, which goes along with the results reported here." (PMID 28619046, 2017). "Moreover, the identification of CTCF as a key player in this model is particularly relevant given the recent identification of human CTCF mutations in individuals with intellectual disability." (PMID 24990380, 2014). "CTCF haploinsufficiency resulting from germline or de novo genetic mutations in CTCF (including genetic deletion, frameshift mutations or missense mutation) causes intellectual disability in humans; now classified as autosomal dominant mental retardation (MRD21; OMIM #615502)." (PMID 30513694, 2018). "CTCF is crucial for NPC proliferation, differentiation, and survival, and CTCF mutations are linked to neurological disorders such as intellectual disability, autism spectrum disorders, and neurodegenerative diseases." (PMID 41296854, 2025). "For instance, a female patient with a de novo c.1024C>T, p.Arg342Cys variant in the CTCF gene exhibited mild intellectual disability, a flat face, upslanting palpebral fissures, and a broad nose." (PMID 37664546, 2023).
Intellectual disability (continued). "Interestingly, two individuals with an intellectual disability and diagnosed with CTCF heterozygous deletions exhibited hypermethylation at nearly 300 CTCF binding sites genome-wide." (PMID 34181707, 2021). "Transcriptome sequencing on lymphocyte messenger RNA from patients with intellectual disability (MIM 604167), harbouring mutant CTCF, and healthy individuals identified SEC14L1 as the top-ranked dysregulated gene in patients." (PMID 25716334, 2015).
leukemia (19 papers, 2014 to 2026). A malignant (clonal) hematologic disorder, involving hematopoietic stem cells and characterized by the presence of primitive or atypical myeloid or lymphoid cells in the bone marrow and the blood. "Here, we investigated the role of CTCF during erythroid differentiation using two complementary models: pluripotent K562 leukemia cells and primary human CD34+ hematopoietic stem/progenitor cells, each induced toward the erythroid lineage by distinct stimuli." (PMID 42072669, 2026). "Is AF4 a potential link between MECOM-rearranged leukemia and CTCF pathways, given that both bind to acetylated H3K9/18/27?" (PMID 40255434, 2025). "CTCF mutations, when layered onto GATA1 mutation, potentiate evolution into clinical leukemia, defined by unlimited replicative potential and impaired ability to differentiate." (PMID 36037342, 2022). "It is known that the transcriptional regulation of MYC is vulnerable to CTCF in the MLL-rearranged leukemia cell line SEM due to addiction of enhancer/promoter looping regulation at three-dimensional chromatin architecture." (PMID 34429148, 2021). "These commonalities suggest a shared mechanism for EVI1 activation in all 3q26-rearranged leukemias, whereby an active hematopoietic enhancer is hijacked by a CTCF-mediated loop with the EVI1 promoter." (PMID 34584081, 2021). "Our previous genome-wide microarray analysis of 100 Chinese pediatric ALL cases indicated that CTCF is up-regulated in leukemia cells." (PMID 24393203, 2014). "Upon DNA demethylation in leukemia cells, the recruitment of CTCF and its binding partners is partially restored." (PMID 24498324, 2014). "Using leukemia cell line Nalm-6, we demonstrated that knock-down of CTCF increased cell apoptosis and decreased cell viability; conversely, over-expression of CTCF rescued cells from apoptosis and enhanced cell proliferation." (PMID 24393203, 2014). "The potential oncogenic mechanism of CTCF and related pathways in leukemogenesis were investigated in leukemia cell lines." (PMID 24393203, 2014). "Similarly, a role for CTCF has been established in normal hematopoietic development; however its involvement in leukemia remains elusive." (PMID 24498324, 2014). "Thus, CTCF boundaries that are involved in determining specific topology of leukemic genome and gene expression programs can potentially be targeted against pathogenesis of leukemia." (PMID 32086528, 2020). "On comparison of our Capture-C data with CTCF ChIP-seq data (an ENCODE data set from K562 cells, ENCSR000DMA) that demarcates compartment boundaries, the major interaction site appears to be clustered at the 3′ end of BCL-2, thus marking a putative 3′ enhancer in MLL-AF4 leukemia cells." (PMID 27856324, 2017). "In the case of NUP98-rearranged leukemia cells, NUP98-HOXA9 fusion–mediated phase separation induced CTCF-independent chromatin loops." (PMID 39883527, 2025). "This identified top 10 TFs involving in hematopoietic cells proliferation and differentiation (SPIB, ATF4) and pathogenesis of leukemia (CEBPB, CTCF)." (PMID 38693103, 2024). "In normally differentiating myeloid cells both CTCF and SMARCA5 together with members of the Cohesin complex are recruited to the SPI1 gene, a key hematopoiesis regulator and leukemia suppressor." (PMID 24498324, 2014). "Thus, HoxBlinc lncRNA regulated CTCF-independent TAD boundaries and TAD/sub-TAD formation in NUP98-rearranged leukemia." (PMID 39883527, 2025). "Accordingly, ChIP-seq revealed constitutive binding of CTCF to this location across various leukemias, including not only 3q26-rearranged AMLs but also other AMLs and acute lymphoid leukemia." (PMID 34584081, 2021). "Here, the authors perform proteogenomic and Hi-C analyses of this leukemia and the ETV6/RUNX1 subtype and show that CTCF and cohesin expression are low in hyperdiploid cases and transcriptional dysregulation in relation to topologically associating domain borders in some of these cases." (PMID 30944321, 2019).
leukemia (continued). "Thus in leukemia cells, AZA exposes newly hypomethylated sites to CTCF that together with SMARCA5 bind and control PU.1 expression." (PMID 24498324, 2014). "CTCF expression in pediatric leukemia cells has not been investigated." (PMID 24393203, 2014).
lung carcinoma (18 papers, 2013 to 2026). "For example, CTCF mutations of E616K or E626K are associated with melanoma and lung cancers, respectively." (PMID 39720519, 2024). "For example, a recent GWAS of a Chinese population identified 3 index SNPs statistically associated with increased risk of lung cancer that are located within CTCF ChIP-seq peaks in the A549 lung cancer cell line." (PMID 26719772, 2015). "CTCF has multiple functional roles in chromosomal interactions, leading to gene expression, while its rs60507107 variant correlates with an increased risk of lung cancer." (PMID 36142846, 2022). "Several typical lung cancer-related genes exhibited interactions mediated by CTCF, EZH2, H3K27me3, and especially RNAPII, suggesting a regulatory relationship between the associated chromatin interactions and these genes." (PMID 36702236, 2023). "To investigate the 3D genome architecture and its regulatory function in lung cancer, we performed long-read ChIA-PET associated with CTCF, RNAPII, EZH2, and H3K27me3 in the lung cancer cell line A549 and noncancerous cell line BEAS-2B." (PMID 36702236, 2023). "A cancerous transition mechanism in lung fibroblasts relies upon the deregulated expression of Rb2/p130, which is controlled by CTCF, and has been shown to promote the progression and recurrence of lung cancer after treatment." (PMID 36142846, 2022). "As this software requires cohesin and CTCF peaks as input and these tracks are only available for breast, colorectal and lung cancer, our analysis is limited to those tissue types." (PMID 34257393, 2021). "The SNP rs60507107 is correlated with increased risk of lung cancer, as the A allele reduces the binding affinity of CTCF at a CTCF binding site in the first intron of DAGLA (in 11q12.2), leading to its altered expression in lung cancer." (PMID 34449663, 2021). "In lung cancer progression, it has been reported that CTCF promoted tumor progression." (PMID 39506204, 2024). "Overexpresssion of the CTCF construct with mutated SUMOylation sites in the CTCF N-terminus or C-terminus resulted in a lack of DUSP2 reactivation in the lung cancer H322 and HEK293 cells." (PMID 26833217, 2016). "Analysis of damage patterns at CCCTC-binding factor and SP1 transcription factor binding sites indicates that BPDE damage formation is also suppressed by these DNA-bound proteins, and this damage modulation correlates with mutation patterns at these binding sites in lung cancers." (PMID 41707998, 2026). "In addition, CTCF was upregulated in lung cancer tissues and cells." (PMID 39506204, 2024). "In addition, TIMER 2.0 data showed that CTCF was overexpressed in lung cancer." (PMID 37665741, 2023). "However, as we were only able to obtain cohesin and CTCF peak data for breast, colorectal and lung cancer, the actual relevance of chromatin loops may be underreported in this study." (PMID 34257393, 2021). "Additionally, in lung cancer cells the activity of CCCTC-binding factor (CTCF), which influences Rb2/p130 gene expression is decreased by BORIS, therefore may correlate with progression of lung tumors." (PMID 23086271, 2013). "Major TFs SP1 and CTCF were also identified, highlighting complex transcriptional and post-transcriptional regulation in COPD–lung cancer progression." (PMID 40826767, 2025). "Our findings revealed that in lung cancer tissues or cells, five transcription factors—FOXA1, CEBPB, CTCF, LMNB1, and POLR2A—concurrently regulate the transcription of COL5A1, MMP1, and SERPINE1." (PMID 39551792, 2024). "The second is likely to affect the CTCF protein, which regulates the TERT gene and its over-expression is important in lung cancer." (PMID 30458782, 2018). "Here we show that overexpression of CTCF induced the expression of AATK in HeLa and in the lung cancer cell lines A549 and H322." (PMID 25352953, 2014).
lung carcinoma (continued). "Interestingly, lung cancer-related genes were more enriched in the RNAPII- and CTCF-meditated interactions than randomly selected genes (P < 2.87E−07, chi-square test)." (PMID 36702236, 2023). "In this study, we used A549 lung cancer cells and noncancerous BEAS-2B epithelial cells as model systems and applied long-read ChIA-PET to map global chromatin interactions associated with different factors, including RNA polymerase II (RNAPII), CCCTC-binding factor (CTCF), EZH2, and H3K27me3." (PMID 36702236, 2023).
neuroblastoma (17 papers, 2017 to 2025). Neuroblastoma (NB) is the most common solid, extracranial childhood tumor. "Conversely, ncRNA MYCNOS was shown to be important in recruiting CTCF to the MYCN promoter in neuroblastoma cell lines, whereas eRNAs recruit CTCF to the boundary of the INK4a/ARF TAD in HeLa cells." (PMID 41296854, 2025). "We used the rat DRG/mouse neuroblastoma hybrid F11 cell line which expresses Cacna1b, to determine if CTCF binds Cacna1b e37a locus in a cell, and to test if CTCF levels influence Cacna1b e37a splicing." (PMID 32213287, 2020). "For example, lncRNA MYCNOS upregulates MYCN expression in neuroblastoma by recruiting CTCF to promoter region of this gene to induce chromatin remodeling." (PMID 32719429, 2020). "A recent study reported that CTCF promoted cell invasion and tumor metastasis in neuroblastoma, which further supports our findings." (PMID 28977939, 2017). "A recent study reported that CTCF exhibits oncogenic activity that enhances the aggressiveness and progression of neuroblastoma by promoting growth, invasion, and metastasis in neuroblastoma cells." (PMID 29212169, 2017). "In addition, CCCTC-binding factor (CTCF) cooperates with noncoding RNA MYCNOS to promote neuroblastoma progression through facilitating MYCN expression." (PMID 36539767, 2022). "The strong CTCF ChIP‐Seq signal covering rs2535629 indicated that CTCF bound to the genomic region containing rs2535629 in neuronal cells and tumor cell lines from the human brain (including neuroblastoma and medulloblastoma cell lines) in vivo." (PMID 34978167, 2022). "To test if rs2535629 regulates the expression of its eQTL genes by interacting with CTCF, we knocked down CTCF expression in SH‐SY5Y (a neuroblastoma cell line) and U251 (a human glioblastoma cell line) cells." (PMID 34978167, 2022). "In neuroblastoma, HNRNPU activates the CCCTC-binding factor (CTCF) by binding to hepatocyte nuclear factor 4 alpha (HNF4A)-derived long noncoding RNA (HNF4A-AS1)." (PMID 36012592, 2022). "For example, overexpression of lncRNA FOXD3-AS1 induces neuronal differentiation and decreases the aggressiveness of neuroblastoma cells through interacting with PARP1 and inhibiting the activation of CCCTC-binding factor (CTCF)." (PMID 29776974, 2018). "Moreover, ectopic over‐expression of FOXD3‐AS1 impairs the aggressiveness of neuroblastoma cells through interacting with PARP1 to inhibit the poly(ADP‐ribosyl)ation and activation of CTCF, thereby repressing downstream tumor‐suppressive genes expression." (PMID 29923329, 2018).